CPD (carboxypeptidase D)
Description:
Functions in the processing of proteins and peptides in the secretory pathway. Mechanistically, cleaves exclusively C-terminal basic residues. By removing terminal residues, can modulate the activity, stability, and receptor-binding properties of bioactive peptides. (Microbial infection) Acts as an alternative entry receptor for adeno-associated virus (AAV).
Synonyms: GP180
Tractability: Antibody: UniProt places it where antibodies can reach, with medium confidence; UniProt predicts a signal peptide or a membrane-spanning region; its Gene Ontology location is reachable by antibodies, with medium confidence. PROTAC: ubiquitination databases record sites on it; its protein half-life has been measured.
Target class: Enzyme; Hydrolase
Gene: Protein-coding gene on chromosome 17 (30,378,922 to 30,469,989, forward strand). Ensembl gene ENSG00000108582.
Subcellular location: Cell membrane
Subcellular location (Human Protein Atlas): Cytosol; Nucleoli
Pathways (Reactome):
Signal Transduction: RND1 GTPase cycle; RND3 GTPase cycle
Vesicle-mediated transport: Golgi Associated Vesicle Biogenesis
Gene Ontology:
Molecular function: metallocarboxypeptidase activity; serine-type carboxypeptidase activity; zinc ion binding
Biological process: peptide metabolic process; protein processing; proteolysis
Cellular component: extracellular exosome; membrane; plasma membrane
Genetic constraint (gnomAD): Loss-of-function variants: 57 observed, 113.33 expected, observed/expected ratio (o/e) 0.5, 90% interval 0.41 to 0.63. The upper end of that interval is the gene's LOEUF score, 0.63, which puts it in group 2 of 6, group 1 being the genes least tolerant of losing a copy. Missense variants: 1,354 observed, 1,569.5 expected, observed/expected ratio (o/e) 0.86, 90% interval 0.82 to 0.9. Synonymous variants: 608 observed, 575.14 expected, observed/expected ratio (o/e) 1.06, 90% interval 0.99 to 1.13.
Homologues: Orthologues: chimpanzee CPD (99% identical), macaque CPD (98% identical), rabbit CPD (95% identical), dog CPD (94% identical), pig CPD (94% identical), rat Cpd (91% identical), mouse Cpd (91% identical), guinea pig CPD (91% identical), tropical clawed frog cpd (67% identical), zebrafish cpda (59% identical), zebrafish cpdb (42% identical), Drosophila melanogaster svr (33% identical), and 1 more. Paralogues in human: AEBP1 (17% identical), CPXM1 (16% identical), CPZ (16% identical), CPXM2 (16% identical), CPE (16% identical), CPN1 (15% identical), CPM (14% identical).
Diseases named in the same sentence as CPD in open-access papers:
CPD is named in the same sentence as 16 diseases in open-access papers, as found by Europe PMC text mining. Sharing a sentence is not in itself a finding about the gene and the disease. The quoted sentences say what the papers report.
breast carcinoma (1 paper, 2022). "Increased carboxypeptidase-D expression was associated with the upregulation of progression markers VEGF-C and Runx2 during breast cancer progression." (PMID 35686102, 2022).
glioma (1 paper, 2022). A benign or malignant brain and spinal cord tumor that arises from glial cells (astrocytes, oligodendrocytes, ependymal cells). "CPD protein is known to process pro-IGF1R into its mature form and we recently showed that CPD is also involved in maturation of MET receptor protein specifically in glioma cells." (PMID 36443674, 2022).
lung adenocarcinoma (1 paper, 2022). A carcinoma that arises from the lung and is characterized by the presence of malignant glandular epithelial cells. "FURIN is also strongly associated with carboxypeptidase D (CPD), recently reported to be required for pro-IGF1R maturation in lung adenocarcinoma." (PMID 35768873, 2022).
lung carcinoma (1 paper, 2022). "Recently, genome-wide CRISPR screening in 3D lung cancer spheroids found that the loss of carboxypeptidase D reduced tumor growth and its expression correlates with patient outcomes in lung cancer patients." (PMID 35686102, 2022).
Nephroblastoma (1 paper, 2023). An embryonal neoplasm characterized by the presence of epithelial, mesenchymal, and blastema components. "We screened four highly expressed m6A-related genes (ADGRG2, CPD, CTHRC1, LRTM2) in nephroblastoma and constructed an effective diagnostic model based on these genes." (PMID 37938417, 2023).
prostate carcinoma (1 paper, 2022). A carcinoma that arises from epithelial cells of the prostate gland. "Elevated carboxypeptidase-D played an anti-apoptotic activity in prostate cancer, which is inhibited by combined prolactin receptor and androgen receptor targeting." (PMID 35686102, 2022).
cancer (4 papers, 2015 to 2024). A tumor composed of atypical neoplastic, often pleomorphic cells that invade other tissues. "The most frequently altered genes were CPD and CNOT2, whose overexpression was associated with survival, inhibition of apoptosis and angiogenesis in different cancer types." (PMID 31817495, 2019). "For combined overexpression of PNKD in mice (cPD‐KI Kp mice), we found that MR‐1 can not only accelerate the progression and death of NSCLC, but also enable metastasis, while cPD‐KO Kp mice does not suffer from cancer." (PMID 38342606, 2024).
tumor (4 papers, 2019 to 2023). "The data showed that the some of the candidate genes form chimeras with a variety of partners in different tumor types and the most frequently rearranged genes were CPD and CNOT2." (PMID 31817495, 2019). "The Carboxypeptidase-D is known to be involved in the intracellular NO production, which is known to have some roles in the progression, invasion, and angiogenesis of the tumor." (PMID 31697718, 2019).
infection (2 papers, 2020 to 2022). The state of being infected such as from the introduction of a foreign agent such as serum, vaccine, antigenic substance or organism. "In the 72 h infection group, the mRNA expression was up-regulated and the protein expression was down-regulated in seven groups, namely the TNXB, NFIA, PROC, SPIN1, NR2C2 nuclear receptor subfamily 2 group C member 2, Carboxypeptidase D and ARHGAP11B." (PMID 36496794, 2022). "In the 72 h infection group, the mRNA expression was up-regulated and the protein expression was down-regulated in 7 groups, namely the TNXB, NFIA, PROC, SPIN1, NR2C2 nuclear receptor subfamily 2 group C member 2, Carboxypeptidase D and ARHGAP11B." (PMID 36496794, 2022).
CPD also shares sentences with these, for which no sentence is quoted: osteoporosis (2 papers); colorectal cancer (1); esophageal carcinoma (1); hepatocellular carcinoma (1); hypernephroma (1); Insulin resistance (1); neuroblastoma (1).